FAM167B (family with sequence similarity 167 member B)
Synonyms: C1orf90; MGC10820; DIORA-2
Tractability: PROTAC: ubiquitination databases record sites on it.
Gene: Protein-coding gene on chromosome 1 (32,247,222 to 32,248,856, forward strand). Ensembl gene ENSG00000183615.
Subcellular location (Human Protein Atlas): Actin filaments
Gene Ontology:
Molecular function: protein binding
Genetic constraint (gnomAD): Loss-of-function variants: 7 observed, 11.85 expected, observed/expected ratio (o/e) 0.59, 90% interval 0.34 to 1.11. The upper end of that interval is the gene's LOEUF score, 1.11, which puts it in group 4 of 6, group 1 being the genes least tolerant of losing a copy. Missense variants: 207 observed, 178.93 expected, observed/expected ratio (o/e) 1.16, 90% interval 1.03 to 1.3. Synonymous variants: 100 observed, 80.95 expected, observed/expected ratio (o/e) 1.24, 90% interval 1.05 to 1.46.
Homologues: Orthologues: chimpanzee FAM167B (100% identical), macaque FAM167B (98% identical), guinea pig FAM167B (91% identical), pig FAM167B (91% identical), dog FAM167B (90% identical), rat Fam167b (89% identical), rabbit FAM167B (88% identical), mouse Fam167b (86% identical), zebrafish fam167b (55% identical), tropical clawed frog fam167b (53% identical). Paralogues in human: FAM167A (44% identical), AARD (19% identical), C20orf202 (16% identical).
Diseases named in the same sentence as FAM167B in open-access papers:
FAM167B is named in the same sentence as 4 diseases in open-access papers, as found by Europe PMC text mining. Sharing a sentence is not in itself a finding about the gene and the disease. The quoted sentences say what the papers report.
cardiac hypertrophy (1 paper, 2023). "Candidate gene identification analyses of exercise-induced cardiac hypertrophy identified five potential regulatory transcripts: IL31ra, Fam167b, Tafa5, Crip3, and Nanos1 (p < 0.01)." (PMID 37178122, 2023).
colon cancer (1 paper, 2025). "And, reverse transcription-quantitative polymerase chain reaction (RT-qPCR) analyse indicated that compared with FAM167B, PCDH17 expression was significantly upregulated in vascular endothelial cells isolated from colon cancer than normal tissue (P < 0.05)." (PMID 39837826, 2025).
tumor (2 papers, 2025). "First, we detected the mRNA expression of 21 risk genes and found that GDPD3, ITGAX, and FAM167B were significantly overexpressed in tumor tissues." (PMID 41562071, 2025). "Among them, PCDH17 and FAM167B were specifically expressed in the tumor endothelial cells than other genes." (PMID 39837826, 2025). "Moreover, single-cell RNA sequencing data analysis further revealed that PCDH17 was more specifically higher expressed in tumor endothelium than FAM167B." (PMID 39837826, 2025).
FAM167B also shares sentences with these, for which no sentence is quoted: prostate carcinoma (1 paper).